BRAF (B-Raf proto-oncogene, serine/threonine kinase)
Diseases named in the same sentence as BRAF in open-access papers (continued):
Sharing a sentence is not in itself a finding about the gene and the disease.
cutaneous melanoma (continued). "Globally, the infrequent rate of BRAF V600E mutation observed in MM limits the efficacy of BRAF inhibitors, largely used in cutaneous melanoma, while the higher NRAS and c-KIT mutations rates make them potentially susceptible to NRAS and c-Kit target therapies." (PMID 35059992, 2022). "BRAF is mutated in about 50% of cutaneous melanomas and in patients with BRAF-mutated metastatic cutaneous melanoma multiple therapeutic options are currently available: BRAF-MEK inhibitors targeted therapies, AntiPD1, and AntiCTLA4 immune checkpoint inhibitors." (PMID 36046043, 2022). "We identified 27 cutaneous melanoma cases with BRAF mutations, of which 21 (78%) could also be detected by the Idylla BRAF and BRAF/NRAS cartridges if run." (PMID 35627184, 2022). "We hypothesize that some BRAF-mutated mucosal melanomas might actually represent metastases of regressed cutaneous melanomas." (PMID 34142226, 2022). "Further, BRAF is mutated in approximately 50% of cutaneous melanoma cases in human patients." (PMID 35559262, 2022). "Molecular analysis might help to differentiate as mucosal melanomas frequently harbor KIT or NRAS mutations and only rarely BRAF mutations, while BRAF mutations are common in primary cutaneous melanomas." (PMID 34142226, 2022). "Cutaneous melanoma and lung adenocarcinoma contained the largest number of patients with an approved actionable marker detected by all sequencing types which was due to the high prevalence of BRAF V600 hotspot and EGFR mutations, respectively." (PMID 35849877, 2022). "The aim of our retrospective study was to know whether BRAF mutations influence the prognostic value of miR-125b, miR-200c and miR-205 intratumoral expression in primary cutaneous melanomas." (PMID 35326682, 2022). "•Approximately 60% of cutaneous melanomas harbor an activating BRAF gene mutation." (PMID 35492830, 2022). "Thus, when confronted with a BRAF-mutated mucosal melanoma, one should be wary of metastatic cutaneous melanoma and meticulously examine the skin of the patient." (PMID 34142226, 2022). "However, there are no studies on the potential associations of the genetic alterations of the BRAF gene with miRNA expression in primary cutaneous melanomas." (PMID 35326682, 2022). "BRAF V600 mutations have been detected in nearly 50% of all cutaneous melanoma patients." (PMID 33801689, 2021). "Although targeted therapy has evolved in the last years and significantly improved the prognosis of patients with cutaneous melanoma, its use in vulvar and vaginal melanomas is still limited by the different mutagenic profiles involving fewer BRAF mutations and more c-KIT, NF1 and SF3B1 mutations." (PMID 34209084, 2021). "For example, whereas mutations in the classic TSG NF1 interact with CNA loss in most cancer types (62.5%), the driver mutations in BRAF only interact with CNA gain in one of the four cancer types in which it is significantly mutated (skin cutaneous melanoma; SKCM)." (PMID 34862370, 2021). "BRAF mutations in cutaneous melanoma are most common on the trunk (affecting less frequently the head and neck), on skin without marked solar elastosis and in younger age, thus suggesting a physiopathology role for intermittent UV exposition in early life rather than chronic sun damage." (PMID 33801689, 2021). "BRAF is less common in mucosal melanomas than cutaneous melanomas, and this analysis cohort had a higher proportion of mucosal melanoma and this could partly explain the low prevalence of BRAF mutations." (PMID 34568037, 2021). "Somatic mutations of BRAF gene have been found in almost 47% of sporadic cutaneous melanomas." (PMID 34698264, 2021). "In addition, BRAF gene had 270 and 311 driver mutations in skin cutaneous melanoma (SKCM) and THCA, respectively." (PMID 33179738, 2021). "A mutation in BRAF, a gene often mutated in cutaneous melanoma, was identified in iris melanoma." (PMID 33396957, 2020).
cutaneous melanoma (continued). "However, the same BRAF mutation as in cutaneous melanoma has been found in some iris melanomas and in a fraction of cells of some posterior UMs." (PMID 32998469, 2020). "Finally, the loss of function of PTEN is observed in about 10–35% of cutaneous melanomas, where it confers resistance to BRAF inhibitors." (PMID 33003469, 2020). "Targeted treatment for conjunctival melanoma harboring a BRAF mutation could be considered since the genetic profile is similar to that of cutaneous melanoma in which BRAF/MEK inhibitors are used." (PMID 33396957, 2020). "The BRAF mutations occur in about 50% of patients with skin melanoma." (PMID 31231466, 2019). "Indeed, nearly half of cutaneous melanomas harbor activating BRAF V600E/K mutations, and therefore, can be treated with BRAF kinase inhibitors in combination with an MEK inhibitor." (PMID 31398831, 2019). "While hundreds of genomes of cutaneous melanoma have now been sequenced, defining a landscape that is replete with UV-induced mutations and driver mutations in genes such as BRAF, the genomes of tumors that develop at mucosal sites have not been as well characterized." (PMID 30664638, 2019). "Exon 15 BRAF V600E variant was most frequent in cutaneous melanoma with a UV signature." (PMID 31581559, 2019). "For example, for thymomas the CIMLR subtypes perform better at predicting survival than histological classification, while the CIMLR subtypes of cutaneous melanoma are much better at predicting survival than classification based on BRAF, RAS, and NF1 mutations." (PMID 30367051, 2018). "A significant proportion of cutaneous melanomas harbor recurring (hot spot) mutations in BRAF (approximately 50%), RAS (approximately 20%), and/or NF1 (approximately 25%) genes, and these mutations can be associated with constitutive activation of the MAPK signaling pathway." (PMID 29385676, 2018). "The BRAF and TERTp mutations may cooperate in cutaneous melanoma and recent evidence indicates that their combination can be used to identify tumours with aggressive behaviour." (PMID 29751586, 2018). "Also of note, we showed that two patients with cutaneous melanoma, including one with a BRAF L597R mutation, achieved partial responses that lasted approximately 4 months, suggesting evidence of preliminary antitumor activity with TAK-733." (PMID 27650277, 2017). "Approximately half of all cutaneous melanomas display somatic mutations in the BRAF gene and in 90% of those the mutation is a single amino acid substitution from valine to glutamic acid at codon 600 in exon 15 (BRAF V600E)." (PMID 28429064, 2017). "Importantly, uveal melanoma shares with cutaneous melanoma the addiction to high levels of ERK activity, but lack NRAS or BRAF mutations that are a hallmark of cutaneous melanoma." (PMID 27034005, 2016). "Cutaneous melanomas that harbor the BRAF (V600E) mutation can be treated with BRAF inhibitors." (PMID 26262638, 2015). "Given the prevalence of somatic activating mutations in cutaneous melanomas, we first assessed BRAF mutational status in the initial eCTC populations from 11 patients: V600 activating mutations in BRAF were determined using primer-specific RT/PCR and size analysis." (PMID 26267609, 2015). "This demonstrates that the mutation is most likely a clonal event in cutaneous melanoma and would imply that the alteration into different tumor cell morphologies occurs at a later stage in time, that is, after the BRAF mutation is acquired, for example, by epigenetic mechanisms." (PMID 25526463, 2014).
cutaneous melanoma (continued). "Interestingly with respect to cutaneous melanomas, the frequency of BRAF mutations was 66% in Caucasian patients with cutaneous melanomas while the frequency was only 25.5% in Chinese patients with cutaneous melanomas." (PMID 25280020, 2014). "While our finding of few BRAF mutations in visceral metastases from cutaneous melanomas contrasts the finding of others, due to a limited number of observation this discrepancy may be caused by chance only." (PMID 23673558, 2013). "Constitutive MAPK activation seems to be a common event in both skin and uveal melanomas, although it occurs through different mechanisms: in skin melanoma, through BRAF and NRAS activating mutations, and in uveal melanoma MAPK activation can occur through GNAQ activating mutations." (PMID 23904987, 2013). "BRAF mutations within activation segment in exon 15 in cutaneous melanoma metastases." (PMID 23555633, 2013). "A single mutation in BRAF (V600E) is present in about 50–60% of human cutaneous melanomas." (PMID 22220282, 2011). "Determining the mutation status of the tumor could be useful with regards to therapeutic consequences, since several studies have shown an improved progression-free survival and overall survival, in patients with metastasized cutaneous melanoma harboring a BRAF mutation, using BRAF inhibitors." (PMID 34071371, 2021). "Therefore, most cutaneous melanomas have a homogeneous BRAF mutation status within a single tumor." (PMID 32143442, 2020). "However, mainly because of primary and acquired resistance to treatments, the majority of patients will ultimately relapse, and only patients harboring a BRAF mutation, observed in about 50% of cutaneous melanoma, can receive a targeted treatment with BRAF and MEK inhibitors." (PMID 32850962, 2020). "Similarly to cutaneous melanoma, up to 50% of conjunctival melanomas harbor BRAF mutations." (PMID 31024839, 2019). "Similarly, in cutaneous melanoma BRAF mutations are more predominant among younger patients." (PMID 31683701, 2019). "The most significantly associated mutated driver gene was BRAF, observed across multiple cancer types, including THCA and skin cutaneous melanoma (SKCM)." (PMID 39822281, 2025). "Malignant melanoma of the skin is a typical example showing that our knowledge on genetics (BRAF is a driver oncogene) and biology (it is an immunosensitive cancer) was sufficient to fundamentally change clinical practice." (PMID 40361349, 2025). "BRAF testing of cutaneous melanomas increased from 2016 to 2019 then decreased from 2020 to 2021; there was no regional variation in this trend across England." (PMID 40902091, 2025). "BRAF + MEK inhibitors demonstrate the greatest clinical benefit in BRAF V600–mutant cutaneous melanomas, achieving high response rates (~65–75%) and significant improvements in survival outcomes." (PMID 41302945, 2025). "PARM exhibits a distinct molecular profile characterized by a notably low frequency of BRAF and NRAS driver mutations, occurring in less than 10% of cases compared to over 50% in cutaneous melanoma." (PMID 41458594, 2025). "This is consistent to current literature that BRAF, HRAS, KRAS or KIT mutations occur rarely in meningeal MCs and are more commonly observed in cutaneous melanoma." (PMID 41324772, 2025). "The most commonly mutated genes were TERT, BRAF, NRAS, and CDKN2A, consistent with known patterns of mutations in cutaneous melanoma." (PMID 39422848, 2025). "Genomic analyses have revealed that oncogenic mutations in genes such as BRAF and NRAS dominate the landscape of cutaneous melanoma, frequently initiating aberrant signaling pathways that foster unchecked cellular proliferation and survival." (PMID 40607411, 2025).
cutaneous melanoma (continued). "According to the Cancer Genome Atlas (TCGA) classification, cutaneous melanoma comprises four main subtypes: BRAF-mutant (~50%), NRAS-mutant (~20%), NF1-mutant (~10–15%) and triple negative/wild-type (~10–15%)." (PMID 41465101, 2025). "In the retrospective study aimed to explore the effects of BRAF and NRAS mutations on the effectiveness of ICIs in 1764 patients with advanced cutaneous melanoma." (PMID 39757723, 2025). "Novel therapeutic approaches include immunotherapy and targeted therapy (BRAF/MEK or KIT inhibitors), although mutation profiles differ from cutaneous melanoma, with KIT and NRAS mutations more common than BRAF." (PMID 41002705, 2025). "The Cancer Genome Atlas Network classifies cutaneous melanoma into four molecular subtypes based solely on genetic variation: BRAF-mutant (52%), RAS-mutant (28%), NF1-mutant (14%), and triple wild-type (6%)." (PMID 41001300, 2025). "To validate our finding that BRAF mutation stratifies RFS in patients treated with adjuvant anti‐PD1, we reviewed an external cohort of patients with stage III cutaneous melanoma (n = 101)." (PMID 41342263, 2025). "Main patient characteristics included cutaneous melanoma 80%, LDH<ULN in 55% of patients, M1c stage in 31%, and BRAF V600 mutation in 37% of patients." (PMID 40821786, 2025). "For unresectable PMML that is BRAF-wild type, as in this patient, a PD-1 containing regimen is rational and supported by extrapolation from large randomized trials in cutaneous melanoma." (PMID 41384184, 2025). "CM, as well as cutaneous melanoma, frequently exhibits mutations in the TERT, NRAS, and BRAF promoter genes." (PMID 41392397, 2025). "Japanese cutaneous melanomas harbored variants in TERT promoter regions and BRAF in some patients and were associated with sun exposure; however, the frequency was much lower than that in White patients." (PMID 39823560, 2025). "Biologically, these tumors exhibit low mutational burden with scarce BRAF (3–11%) mutations but more frequent KIT (22%) and NRAS (5–14%) aberrations, contrasting with the UV-driven mutation profiles seen in cutaneous melanoma." (PMID 41002705, 2025). "ICIs also demonstrate efficacy for patients with both BRAF-mutant and wild-type advanced cutaneous melanoma." (PMID 41295253, 2025). "NF1 mutations are present in 5% of BRAF-, 13% of NRAS-, and 50% of RASA2-mutant cutaneous melanomas." (PMID 39804140, 2025). "Other non-V600 mutations and BRAF fusions are found in about 4–14% of primary cutaneous melanoma cases, yet since they are part of the BRAF class II and III mutations they generally respond poorly to combined BRAF and MEK inhibition." (PMID 39207855, 2024). "We observed that PRSS1 and CTCF mutations in lung adenocarcinomas and skin melanomas show similar resistance-conferring effects to KRAS and NRAS mutations when treated with EGFR and BRAF inhibitors." (PMID 39160568, 2024). "It should also be noted that recent studies have found that the use of MEK inhibitors in conjunction with BRAF inhibitors has significantly improved outcomes for patients with BRAF-positive cutaneous melanoma." (PMID 39518150, 2024). "In this study, we aim to investigate the therapeutic efficacy and molecular mechanism underlying RC48 alone or in combination with dabrafenib in both in vitro and in vivo models of BRAF-mutant cutaneous melanoma." (PMID 38594618, 2024). "This phenomenon can be noted in the Dabrafenib and Trametinib combination in metastatic BRAF-mutant cutaneous melanoma." (PMID 38390492, 2024). "BRAF V600E substitutions are typical for a variety of cancers including skin melanoma, but rarely found in sarcomas." (PMID 39018206, 2024). "BRAF and NRAS mutations have been reported in 41% and 18% of human cutaneous melanomas, respectively, and KIT mutations in 8.6–25% of acral/mucosal/chronically sun-damaged skin melanomas." (PMID 38397192, 2024).
cutaneous melanoma (continued). "To further investigate the clinical relevance of our findings, we analyzed the RNA sequencing results of BRAF V600E mutant skin cutaneous melanoma (SKCM) in The Cancer Genome Atlas (TCGA) database." (PMID 38965534, 2024). "As BRAF V600E testing is paramount in routine clinical testing in cutaneous melanoma, we aimed to compare ddPCR sensitivity with a CE-IVD validated RT-PCR assay when screening for these mutations in paraffin-embedded tissue samples." (PMID 38396984, 2024). "BRAF and NRAS are mutant genes in skin cutaneous melanoma associated with different tumor immune microenvironments." (PMID 38438381, 2024). "Approximately 90% of cutaneous melanomas exhibit abnormal activation of the mitogen-activated protein kinase (MAPK) pathway, primarily because of mutations in the BRAF gene." (PMID 39202970, 2024). "Mucosal melanomas have a mutational profile characterized by KIT as the most frequent mutations (20–25% of cases), followed by BRAF and NRAS mutations (whose frequency is lower than that observed in cutaneous melanomas) and NF1 mutations." (PMID 39727691, 2024). "Of the cutaneous melanoma samples, 81, 55, 19, and 20 samples were BRAF-, (N)RAS-, or NF1-mutant or TWT, respectively." (PMID 38758740, 2024). "The advent of molecular stratification and personalized medicine such as the current approaches for BRAF mutant cutaneous melanoma and KIT-mutant gastrointestinal tumors offer hope to these patients." (PMID 38417447, 2024). "Here, we utilized a cell-based transposon mutagenesis method to identify mechanisms of BRAF inhibitor resistance in a model of cutaneous melanoma." (PMID 38213996, 2024). "We evaluated the therapeutic efficacy of RC48, alone or in combination with dabrafenib, in BRAF-mutant cutaneous melanoma cell lines and cell-derived xenograft (CDX) models." (PMID 38594618, 2024). "New therapeutic regimens (immunotherapy, BRAF, and MEK inhibitors) have shown relapse-free survival in patients with cutaneous melanoma but they are associated with cardiotoxicity." (PMID 38975493, 2024). "By enhancing our understanding of targeted therapies and their combinations, our goal is to improve the prognosis and long-term survival of patients with HER2-positive and BRAF-mutant cutaneous melanoma." (PMID 38594618, 2024). "Our findings establish a preclinical foundation for the combined use of an anti-HER2 drug conjugate and a BRAF inhibitor for the treatment of BRAF-mutant cutaneous melanoma." (PMID 38594618, 2024). "Briefly, a 54-year-old woman presented with a BRAF wild-type cutaneous melanoma that was resected in addition to a single positive axillary node." (PMID 38596681, 2024). "Despite this low expression, we showed that RC48 exhibited superior therapeutic efficacy by inducing cell cycle arrest, apoptosis, and inhibiting of cell motility in HER2-positive and BRAF-mutant cutaneous melanoma cells." (PMID 38594618, 2024). "In the publicly available GENIE dataset, looking exclusively at cutaneous melanomas shows that the specific mutation rates within primary tumors were 55 % for TERT, 40 % for BRAF, 7.2 % for KIT, 2.5 % for NRAS, and 1.9 % for CDH1." (PMID 38158497, 2024). "The BRAF gene is located on chromosome 7q and the gains of chromosome 7 are observed in about 50% of patients with primary cutaneous melanomas." (PMID 39727691, 2024). "Immune checkpoint inhibitors are recommended for cutaneous melanomas following progression on BRAF- and MEK-inhibitor treatment." (PMID 38716076, 2024). "The treatment options for patients with skin cutaneous melanoma (SKCM) vary based on BRAF V600E statuses." (PMID 36704723, 2023). "BRAF inhibitors, particularly in combination with MEK inhibitors, have proven to be highly efficient in patients with cutaneous melanoma; however, these mutations have seldom been found in mucosal melanoma." (PMID 38139110, 2023).